INS (insulin)
Diseases named in the same sentence as INS in open-access papers (continued):
Sharing a sentence is not in itself a finding about the gene and the disease.
Insulin resistance (continued). "Human studies have demonstrated elevated iron stores to precede insulin resistance, while lowering serum iron can increase insulin sensitivity." (PMID 28651003, 2017). "Adoptive transfer of B-2 cells exacerbates insulin resistance, whereas depletion of B-2 cells ameliorates insulin sensitivity in obese mice." (PMID 28491871, 2017). "Type 2 diabetes is defined as a metabolic syndrome with a combination of insulin resistance and defective insulin secretion by pancreatic β-cells." (PMID 28620607, 2017). "The majority (90–95%) of DM patients have type 2 DM (T2DM), which is characterized by peripheral insulin resistance and an inability of pancreatic beta cells to compensate for that by increasing insulin secretion." (PMID 28360826, 2017). "Chronic obesity often results in insulin resistance, whereby insulin-responsive tissues fail to execute insulin signaling, prompting further insulin secretion." (PMID 28959684, 2017). "Free fatty acid accumulation in the liver, adipose tissue, and skeletal muscle of obese patients interferes with normal insulin signaling, which will lead to insulin resistance." (PMID 28615046, 2017). "The LBW individuals became significantly more insulin resistant in peripheral tissue in response to HFO (P = 0.03) whereas the NBW individuals selectively developed hepatic insulin resistance (P = 0.0002)." (PMID 28450702, 2017). "Several studies reported that insulin resistance is more associated with VAT mass than with obesity itself showing a possible regional variation in insulin sensitivity." (PMID 28567337, 2017). "T1DM, arising from pancreatic β-cell destruction, is mechanistically distinct from the more common T2DM, which comprises both insulin resistance and impaired insulin secretion." (PMID 28446231, 2017). "Previous research suggests that a chronic increase in circulating insulin can lead to impaired insulin signaling within skeletal muscle, which is thought to be the initial defect leading to insulin resistance and the development of type 2 diabetes." (PMID 29233906, 2017). "In this study, we identified the in vivo ubiquitin-modified proteome in rat liver and determined changes in this ubiquitome under acute insulin stimulation and high-fat and sucrose diet-induced insulin resistance." (PMID 28329008, 2017). "Hepatic insulin sensitivity is provided by HOMA 2-IR as this marker indicates insulin resistance for a value higher than 1.85." (PMID 28497040, 2017). "It elevated the plasma levels of insulin, insulin resistance and leptin but decreased the levels of adiponectin, BMC and BMD." (PMID 29176994, 2017). "In males, the subgroup analysis identified a significant inverse relationship between the insulin resistance indices and BMD of the femur and lumbar spine (marginal association between the HOMA-IR and serum fasting insulin and femoral intertrochanter)." (PMID 28704413, 2017). "Insulin resistance is a state where the produced insulin exerts a suboptimal biological action, resulting in a decrease in the ability of insulin to stimulate skeletal muscle and adipose tissue for glucose uptake." (PMID 28754153, 2017). "To identify a potential role for Dnmts in the pathogenesis of insulin resistance, we compared their expression levels in insulin-sensitive metabolic tissues (i.e. liver, muscle, and adipose depots) in various metabolic settings." (PMID 29091029, 2017). "It is well known that dysregulation of insulin leads to marked alteration in amino acid metabolism, and that histidine supplementation improves insulin resistance and reduces obesity." (PMID 28106113, 2017).
Insulin resistance (continued). "Because beta cells are subjected to high insulin demand in response to hyperglycemia and peripheral insulin resistance, we postulated that expressions of proteins involved at the ER-mitochondrion interface were increased during type 2 diabetes." (PMID 28742858, 2017). "Previous studies have reported that fasting serum insulin levels and insulin resistance index values are inversely correlated with FVC and FEV1." (PMID 28346522, 2017). "Mitochondria have a significant role in glucose-stimulated insulin secretion from pancreatic β cells, with decreases in mitochondrial oxidative activity and ATP synthesis leading to insulin resistance." (PMID 29163354, 2017). "Overall, these findings indicated that S-nitrosation of insulin signaling pathway is required to sustain hypothalamic insulin resistance in obesity." (PMID 28835706, 2017). "T2D is a metabolic disorder characterized by chronic hyperglycemia resulting from insulin resistance and impaired insulin secretion." (PMID 29258603, 2017). "In a study with diabetic mice, treatment with β-glucans of different molecular weights showed a hypoglycemic effect, improving insulin secretion and decreasing insulin resistance when compared to untreated animals." (PMID 28906456, 2017). "Sporadic Alzheimer’s disease (AD) is a metabolic disease relative to impairments in brain insulin signaling and energy metabolism, which lead to increased oxidative stress, inflammation, and aggravation of insulin resistance." (PMID 29258283, 2017). "Insulin resistance and Insulin sensitivity were measured using the homeostatic model assessment (HOMA) and quantitative insulin sensitivity check index (QUICKI) respectively." (PMID 28540283, 2017). "Several methods have been developed for assessing insulin resistance, including plasma insulin level and homeostasis model assessment of insulin resistance (HOMA-IR)." (PMID 28430816, 2017). "The same tendency was seen in the fasting insulin level, which is considered to be an indicator of insulin resistance and this level increases with age." (PMID 28944611, 2017). "Insulin resistance and type II diabetes are characterized by impaired insulin sensitivity and later in the disease, impaired insulin secretion." (PMID 28880231, 2017). "The therapeutic effects of 2-ME on glucose tolerance defects, either via the amelioration of insulin resistance or the stimulation of insulin secretion, are likely dependent on the environments." (PMID 28801594, 2017). "The observed phenomenon of hepatic selective insulin resistance, namely that hepatic glucose production becomes resistant to insulin while de novo lipogenesis remains unabated or even gets enhanced, is a long-standing paradox in T2D27." (PMID 29118381, 2017). "Some studies have shown that OPN is causally involved in the pathogenesis of insulin resistance and type 2 diabetes, while other studies have shown that OPN is a protective islet protein preserving insulin secretion." (PMID 28194185, 2017). "Type 2 diabetes (T2D) is characterized by chronic hyperglycemia with progressive failure of pancreatic insulin secretion and increased peripheral insulin resistance." (PMID 28099913, 2017). "The physiological defects in T2D that is reduced insulin sensitivity, insulin resistance and combined with impaired insulin secretion." (PMID 28612706, 2017). "Increased insulin levels as a result of insulin resistance also play a dynamic role in L-arginine and NO pathway." (PMID 28526818, 2017). "Our results reveal that the degree of insulin sensitivity was remarkably decreased by 6.9% (measured by McAuley-index) after 2-months de-training, indicating that insulin resistance had obviously developed." (PMID 28738856, 2017). "Insulin resistance and hyperinsulinemia, common features of all these metabolic disorders, contribute to the deregulation of the insulin/IGF axis that plays an important role in cancer progression as well as in CSCs." (PMID 28275367, 2017).
Insulin resistance (continued). "Both protocols of insulin resistance abolished insulin-mediated phosphorylation of Akt and GSK3β, but only IPA treatment induced the inhibitory hyper-phosphorylation of GSK3β at Ser9 (+139 ± 10%)." (PMID 29222408, 2017). "By 16 weeks, C57BL/6J mice reared on FF diet potentially induced features of MS, with elevated levels of triglyceride, cholesterol, and insulin resistance (elevated serum levels of glucose and insulin and low serum levels of ADP)." (PMID 29371918, 2017). "In our study, we confirm insulin resistance, with de-arranged serum levels of glucose, insulin and ADP, and along this hepatic activation of m-TOR, p-mTOR and Akt was also involved." (PMID 29371918, 2017). "Central insulin resistance is thought to result from a combination of impaired insulin receptor signaling and decreases in the transport of insulin across the BBB, which can occur secondary to peripheral glucose intolerance." (PMID 28400713, 2017). "LPS can stimulate the secretion of proinflammatory cytokines, which ultimately impairs insulin sensitivity and promotes insulin resistance-related metabolic disorders." (PMID 28099913, 2017). "Fasting insulin was largely increased in the HFD group, indicating potential insulin resistance, and all three supplemented groups had significantly lowered insulin levels." (PMID 29023387, 2017). "These proteins were correlated with lower systemic insulin resistance and improved insulin signaling in subcutaneous WAT of the MetS patients." (PMID 28820493, 2017). "Impaired insulin secretion and insulin resistance in multiple tissues are the two key mechanisms in the pathophysiology of type 2 diabetes." (PMID 28911155, 2017). "There is progressive insulin resistance starting in the mid-trimester due to production of various placental hormones that serve as insulin antagonists." (PMID 28644881, 2017). "The mean values of the entire group for cardiometabolic risk factors, fasting serum insulin (FSI), homeostasis model assessment of insulin resistance (HOMA-IR) and other parameters were within the normal ranges." (PMID 28469173, 2017). "oxLDL also reduces adiponectin secretion, and this affects systemic insulin resistance because adiponectin improves insulin sensitivity in endothelial cells, hepatocytes, and skeletal muscle cells." (PMID 29081894, 2017). "HOMA revealed significantly greater insulin resistance and steady-state β-cell function, and lower insulin sensitivity compared to low-fat chow-fed mice." (PMID 28352127, 2017). "Insulin resistance is the condition characterized by lowered response of cells to circulating insulin." (PMID 28194257, 2017). "Palmitate induced insulin resistance as indicated by impaired insulin-induced phosphorylation of insulin receptor, Akt, Gsk3β and FoxO1." (PMID 28933767, 2017). "Insulin resistance is a condition in which the response of sensitive tissues to insulin as well as glucose uptake are decreased." (PMID 29113108, 2017). "Many feedbacks/crosstalks have been reported to shape insulin signaling and play a role in the development of hepatic insulin resistance." (PMID 29118381, 2017). "Studies have shown that increased levels of fructose can contribute to liver fat, resulting in insulin resistance as well as alterations in insulin and glucose metabolism." (PMID 28212335, 2017). "In a study conducted by Stanišić and colleagues, Wistar rats received a 10% fructose solution for 8 weeks, and thereafter a significant increase in insulin levels and severe insulin resistance were observed." (PMID 28425939, 2017). "As adiponectin is known to have insulin-sensitizing properties, it is likely that 10,12 CLA-induced subcutaneous fat loss contributes to reduced plasma adiponectin and subsequent insulin resistance." (PMID 28245284, 2017). "Insulin resistance is characterized by reduced sensitivity to insulin and, as a result, impaired ability of insulin to reduce peripheral blood glucose concentration." (PMID 28515345, 2017).
Insulin resistance (continued). "On the other hand, insulin resistance in the hypothalamus reduces insulin-mediated Akt phosphorylation, thereby upregulating overexpression of FoxO1, which results in increased food intake and obesity." (PMID 28684967, 2017). "Previous studies have shown that heavier individuals are more likely to be insulin-resistant and that adiposity and insulin resistance are highly correlated." (PMID 28744376, 2017). "Although insulin levels were lowered by all flavanol fractions, impaired glucose tolerance, insulin resistance, weight gain, and fat mass were most effectively avoided by the oligomer-rich fraction." (PMID 29088075, 2017). "Blood samples were collected over the 14-week study and analyzed for glucose, lipid profile, and CRP, lipid particles, TNF-α, IL-10, insulin, and insulin resistance (IR)." (PMID 29410955, 2017). "It is not surprizing that patients in T2DM were fatter with metabolism syndrome, and their requirements of insulin were higher than T1DM because of the insulin resistance which will lead to more weight gain." (PMID 28538386, 2017). "Female 5αR1-KO mice aged 6 m fed normal chow demonstrated insulin resistance (~35% increased area under curve (AUC) for insulin upon glucose tolerance testing) and hepatic steatosis (~33% increased hepatic triglycerides) compared with controls." (PMID 27647861, 2017). "They improve glucose tolerance and insulin sensitivity in type 2 diabetic patients and in animal models of insulin resistance." (PMID 28298922, 2017). "Fasting plasma glucose was reported in the offspring of high-fat- and carbohydrate-fed dams even in the presence of high levels of plasma insulin, suggesting marked insulin resistance." (PMID 28684678, 2017). "Insufficient insulin secretion to compensate for insulin resistance is also the characteristic of Type 2 diabetes." (PMID 28676747, 2017). "Insulin resistance is an abnormal physiological state that occurs when insulin from pancreatic β-cells is unable to trigger a signal transduction pathway in target organs such as the liver, muscles and adipose tissues." (PMID 29023424, 2017). "In studies using rats, KD also induced glucose intolerance and insulin resistance, despite reduced glucose and insulin levels." (PMID 28534852, 2017). "T2D begins with insulin resistance in which cells fail to respond to and uptake of insulin in the body." (PMID 28612706, 2017). "Insulin resistance is a metabolic disorder characterized by a decrease in sensitivity of insulin receptors within target cells, resulting in the failure of insulin to achieve the desired effect." (PMID 28797289, 2017). "Fasting glucose, insulin, C-peptide levels, and insulin resistance assessed by HOMA-IR decreased significantly 3 months after RDN, whereas there were no significant changes in the control group." (PMID 29082259, 2017). "Previous research showed IL-1β to be a key factor in the development of insulin resistance and suppression of insulin-induced glucose transport." (PMID 28661434, 2017). "We and others have provided evidence about the role of MGO on insulin-resistance in major target tissues for insulin action." (PMID 28106778, 2017). "Insulin resistance in fat cells reduces the normal effects of insulin on lipids and results in reduced uptake of circulating lipids and increased hydrolysis of stored TG." (PMID 28555043, 2017). "A study conducted in 256 pregnant women with normal glucose tolerance found significant reductions in FBG, insulin concentrations and insulin resistance following probiotic supplementation, potentially reducing participants’ GDM risk." (PMID 28475161, 2017). "We postulate that insulin resistance stimulates activation of the PGC‐1a/FNDC5 pathway as a compensatory response in effort to increase insulin sensitivity and attenuate impaired insulin signaling." (PMID 28676551, 2017).
Insulin resistance (continued). "CM individuals also exhibited impaired insulin sensitivity manifested by the Matsuda index and homeostasis model assessment of insulin resistance, which were correlated with CM severity after adjusting for depression." (PMID 28713332, 2017). "While the precise molecular mechanism remains to be elucidated, insulin resistance is always manifested by disturbances in insulin signalling, thus leading to its attenuation." (PMID 28194257, 2017). "Fasting insulin concentration correlates strongly with insulin resistance and HOMA-IR is considered a robust tool for the evaluation of insulin resistance in large epidemiological studies." (PMID 28304338, 2017). "A significant decrease in blood glucose and insulin levels decreased insulin resistance, and improved glucose tolerance was observed in the treatment animals when compared with the fructose-fed animals." (PMID 28798859, 2017). "Insulin resistance is a condition in which the peripheral tissues of the human body becomes resistant to the action of insulin." (PMID 28575103, 2017). "C3aR1 mediates the functions of insulin by modulating insulin resistance, obesity and macrophage function." (PMID 27920259, 2017). "Accumulating clinical evidence suggest that monocytes/macrophages play a critical role in the pathogenesis of insulin resistance by infiltrating insulin target tissues." (PMID 28706484, 2017). "Due to severe insulin resistance, the patients included in the present study had insulin and glucose infused at the time of biopsy sampling." (PMID 28252104, 2017). "Autophagy is important for regulating organelle function and insulin signaling and defective autophagy is closely related to insulin resistance in obesity." (PMID 28534819, 2017). "When insulin resistance develops in type 2 diabetes, the pancreatic insulin secretion is increased in compensation." (PMID 29233100, 2017). "At the age of 1 year and 10 months, the boy returned to our center with a raised random blood glucose (17.2 mmol/L) and severe insulin resistance (insulin >300 μIU/mL and C-peptide 14.30 ng/mL)." (PMID 27612026, 2017). "Since AD is frequently accompanied by insulin resistance, metformin is sought to improve insulin sensitivity in AD patients." (PMID 28922161, 2017). "The results showed that doxycycline not only ameliorated insulin resistance, fasting blood glucose and insulin levels, and lipid profiles in the circulation and liver, but also improved islet morphology and increased glucose-stimulated insulin secretion." (PMID 29089617, 2017). "These molecules play a vital role in the improvement of glucose homeostasis and insulin sensitivity and protection against the development of obesity and insulin resistance." (PMID 28937612, 2017). "The pancreatic islets respond to insulin resistance by increasing their cell mass and the secretion of insulin." (PMID 28294968, 2017). "When cells are insensitive to insulin (or insulin resistance), the pancreatic beta cells produce more and more insulin, which leads to the higher insulin concentration in blood (hyperinsulinemia)." (PMID 28612706, 2017). "Recent experimental advances pointed to the important roles of certain distal part of the insulin signaling network in inducing selective insulin resistance, such as mTORC130, mTORC232, and FoxO68." (PMID 29118381, 2017). "This is an interesting notion in a clinical context since patients that are insulin resistance have a “blunted” response to insulin and subsequent downstream cellular signaling responses." (PMID 29157234, 2017). "An increase in plasma free fatty acid (FFA) concentrations plays a key role in the pathogenesis of insulin resistance through actions that block insulin signal transduction." (PMID 27942693, 2017). "We also show that depot-selective adipose hyperplasia is discordant with suppressed leptin levels and impaired insulin-mediated suppression of lipolysis in severely affected patients, while insulin resistance is seen in all." (PMID 28414270, 2017).